KLF10 (KLF transcription factor 10)
Diseases named in the same sentence as KLF10 in open-access papers (continued):
Sharing a sentence is not in itself a finding about the gene and the disease.
cancer (continued). "Dysregulation of KLF10 has been observed in several human diseases, such as cardiovascular disease, skeletal muscle disease, and cancers." (PMID 35565995, 2022). "Background and Objectives: Krűppel-like factor 10 (KLF10) participates in the tumorigenesis of several human cancers by binding to the GC-rich region within the promoter regions of specific genes." (PMID 35743973, 2022). "Distinguishing the antiproliferative and prometastatic functions of TGFβ makes KLF10 a potential target for the development of therapies for cancers with aberrant TGFβ pathways, such as PDAC." (PMID 34702956, 2021). "KLF10 functions as an anti-oncogene transcription factor via TGF-β signaling in multiple cancers by playing a role in apoptosis, cell cycle regulation, cell growth, and differentiation." (PMID 34635142, 2021). "More importantly, KLF10 has been shown to have anti-proliferative effects and to induce apoptosis in various carcinoma cells." (PMID 34572749, 2021). "In light of the significant prognostic role of KLF10 shown in the present study and the few other studies that drew similar conclusions in relation to various cancers, subsequent studies are needed to develop new screening methods or therapies." (PMID 33379261, 2020). "Pin1 interacts with KLF10 and promotes its protein degradation, blocking the anti-proliferative function of KLF10 in cancer cells." (PMID 32296699, 2020). "Serving as an effector protein of TGFβ-mediated cell growth control and differentiation, KLF10 is well known for its close relationship with TGFβ and consequent pivotal role in various cancers." (PMID 33379261, 2020). "One study found that KLF10 induces apoptosis in the TGF-β signaling pathway of resistant cancer cells and concurrently increases chemosensitivity for treatment with gemcitabine." (PMID 31480737, 2019). "Further understanding of its function and target genes are needed to provide additional insights into the mechanisms of action of KLF10 to understand its role in diseases, including cancer." (PMID 29799499, 2018). "Collectively, these data indicate that KLF10 plays a significant role in various biological processes and diseases, but its role in cancer is still unclear." (PMID 29799499, 2018). "In addition to the Wnt/β-catenin signaling pathway, we demonstrated that KLF10 contributed to the cancer stemness phenotype by transcriptionally regulating Notch-3 and Notch-4 and competing with E74-like ETS transcription factor 3 (ELF3) for promoter binding." (PMID 37958386, 2023). "Because KLF10 might modulate EMT and metabolic reprogramming to regulate cancer stemness, we combined evodiamine with metformin, which elevated KLF10 expression by modulating AMPK phosphorylation, in the orthotopic murine model of PDAC." (PMID 37308977, 2023). "Not only can KLF10 expression be used as a clinical prognostic and risk indicator for PDAC, but it can also serve as a potential therapeutic target to molecularly complement current cancer treatments." (PMID 37239940, 2023). "Radiation-induced KLF10 upregulation was noted in many cancer cell lines and murine models." (PMID 37958386, 2023). "We measured representative transcripts of candidate molecules from 10 signaling pathways essential to cancer stem cell survival to understand the signals governing stem cell homeostasis in Panc-1 cells with or without KLF10 deficiency." (PMID 37308977, 2023). "Decreased KLF10 expression has been found in several human cancers." (PMID 35743973, 2022). "In this context, it has been shown that Klf10 is downregulated in type 2 diabetes and cancer." (PMID 35736488, 2022). "However, all these studies that supported the pro-apoptotic role of KLF10 were conducted in cancer cells while we used primary cells." (PMID 32699233, 2020). "KLF10 effectively represses cancer cell proliferation, with the overexpression of KLF10 reducing cell proliferation in many cancer types while its absence may enhance cell proliferation." (PMID 33379261, 2020).
cancer (continued). "Additionally, ALOX15, which was recently described to participate in the immune response in cancer, was also down regulated in KLF10 mice." (PMID 29930344, 2018). "KLF10 is believed to be a tumor suppressor gene in many cancers, including human colorectal cancer." (PMID 29799499, 2018). "Therefore, this review was conducted to describe and discuss the role and function of KLF10 in diseases, including cancer, with a special emphasis on its signaling with TGF-β." (PMID 29799499, 2018). "One gene involved in free radical scavenging, SOD3, was downregulated, whereas the genes associated with cell cycle or cancer, including GADD45B, ID1, KLF10, CSRNP1, and TM4SF1, were upregulated in F. nucleatum-infected GF(P22) cells when compared to F. nucleatum-infected GF(P4) cells." (PMID 29190775, 2017). "HES1, CTAG2 and KLF10 have all been shown to play a role in cancer biology." (PMID 24885297, 2014). "In pancreatic cancer, KLF10 may transcriptionally activate sirtuin 6 and inhibit epithelial-mesenchymal transition through NF-κB, suppressing the growth and migration ability of cancer cells." (PMID 36761967, 2023). "However, the effects of KLF10 on the cancer stem cell phenotypes of PDAC are still unclear." (PMID 37308977, 2023). "Previous reports have shown that KLF10 may play a critical role in several human cancers." (PMID 35743973, 2022). "In preclinical studies, KLF10 was demonstrated to be correlated with PDAC progression and resistance and it was reported to modulate distant metastasis, cancer stemness, and radio-sensitivity." (PMID 37958386, 2023). "In advanced-stage cancer, TGF-β signaling enhances the EMT whereas KLF10 inhibits TGF-β-induced EMT." (PMID 37958386, 2023). "Among 7912 samples across 18 cancer types, we interestingly observed that the majority of the clock control gene, such as HLF, KLF10, FBXL3, TEF, RORs (RORA, RORB, RORC), and NR1D2, are down-regulated in a wide range of cancers." (PMID 36895015, 2023). "In order to validate the transcription factor role of ZBTB7A to KLF10, transcriptomic data of kidney para-carcinoma tissue in TCGA and normal kidney tissue in GTEx from GEPIA showed significant positive correlation between KLF10 and ZBTB7A." (PMID 36878898, 2023). "Klf10 is described as a tumor suppressor gene through TGF-β-induced growth inhibition; its functions are anti-proliferative and pro-apoptotic in cancer cells." (PMID 35736488, 2022). "Krüppel-like factor 10 (KLF10) has been identified as an important regulator in carcinogenesis and cancer progression." (PMID 32549754, 2020). "Krüppel-like factor 10 (KLF10), a TGFβ early-response gene, has been demonstrated by investigators, including us, to contribute to PDAC radiosensitivity, epithelial - mesenchymal transition, and cancer stemness and progression." (PMID 37596627, 2023). "Unlike TGF-β in advanced cancers, KLF10 loss in two-thirds of patients with PDAC was associated with rapid distant metastasis and radioresistance; thus, KLF10 can serve as a predictive and therapeutic marker for PDAC." (PMID 37958386, 2023). "After KLF10 depletion, an ingenuity pathway analysis (IPA) revealed that pathways, including the Wnt and Notch signaling pathways, were highly upregulated in the “cancer signal pathway” profile." (PMID 37308977, 2023). "KLF10 is a member of the Krüppel-like transcription factor family and acts as a tumor suppressor, mimicking the anti-proliferative effect of TGF-β in various cancer cells." (PMID 32296699, 2020). "The significant correlation between high KLF10 expression and a higher 5-year survival rate was observed in certain subgroups of clinical parameters, including female gender, non-smokers, cancer stage T1, and cancer stage N0." (PMID 33379261, 2020).
metabolic disorders (8 papers, 2021 to 2024). "Recent studies have shown nutritional challenges in reprogramming circadian physiology and increased susceptibility to metabolic diseases in KLF10 KO mice." (PMID 38279278, 2024). "AMPK phosphorylates the KLF10 protein at Thr189 to activate and stabilize it, thereby suppressing srebp-1c expression and regulating lipogenesis and metabolic disorders." (PMID 38279278, 2024). "Given the close association between KLF10 and metabolic disease we measured the glycolysis activity of PDAC cells with genetically manipulated KLF10." (PMID 34702956, 2021). "The desynchrony between circadian timing and the fasting/feeding cycle presumably impairs KLF10 functionality and thus may further exacerbate metabolic disease phenotype." (PMID 34402428, 2021). "Accordingly, we suggest that KLF10 could be a critical target for resolving these metabolic disorders." (PMID 34869587, 2021). "The coordinated regulation of KLF10 and KLF11 manifests in bone cell development, bone diseases, and certain metabolic disorders." (PMID 39272379, 2024). "AMPK activates and stabilizes the KLF10 protein via phosphorylation at Thr189, thereby repressing the expression of SREBP-1C and subsequent lipogenesis pathways and metabolic disorders." (PMID 34869587, 2021). "Taken together, our findings revealed for the first time that AMPK activates and stabilizes the KLF10 protein via phosphorylation at Thr189, thereby repressing the expression of SREBP-1C and subsequent lipogenesis pathways along with metabolic disorders." (PMID 34869587, 2021). "Previous studies indicated that the incidence of metabolic diseases is increased in KLF10 knockout mice and that AMPK can phosphorylate KLF10." (PMID 33485367, 2021). "However, Klf10 knockout mice, which suffer from metabolic disorders, do not develop malignancy." (PMID 34702956, 2021).
infection (5 papers, 2011 to 2022). The state of being infected such as from the introduction of a foreign agent such as serum, vaccine, antigenic substance or organism. "This network appears to be active in the infection situation in mosquitoes, as the KLF10 target genes include the Mondo-Mlx dependent genes pepck as well as the circadian genes tim, vri and cwo." (PMID 35397616, 2022). "The IPA network analysis revealed that infection induced aged GF(P22)-specific DEGs were connected to each other and the upregulated genes (Id1, KLF10, GADD45b, and CSRNP1) were all mainly localized in the nucleus." (PMID 29190775, 2017). "This remarkable pattern indicates that approximately 2/3 of the AhR-regulated genes are the KLF10 target genes as well, supporting the hypothesis that AhR and KLF10 act as a transcriptional axis in response to the infection." (PMID 35397616, 2022).
kidney disease (3 papers, 2019 to 2023). "In this study, network-based analysis of online transcriptional data of human kidney found that KLF10 was closely related to renal function, tubular injury and regeneration in various renal diseases." (PMID 36878898, 2023). "Furthermore, renal tubulointerstitial RNA-seq data of other kidney diseases from Nephroseq database also displayed significant downregulation of KLF10, which validated the vital role of KLF10 in injury renal tubule." (PMID 36878898, 2023). "Moreover, transcriptomic data from tubulointerstitium of other kidney diseases showing decreasing KLF10 revealed the significant role of KLF10 in renal tubules." (PMID 36878898, 2023). "To further study the function of KLF10 in kidney disease, we used KLF10‐KO mice." (PMID 30948420, 2019).
adenocarcinoma (1 paper, 2019). A common cancer characterized by the presence of malignant glandular cells. "A previous study reported that increased Krüppel-like zinc finger transcription factor 10 (Klf10) suppressed TMBIM6 expression in an estrogen-dependent manner and induced cell death in adenocarcinoma cells." (PMID 31336725, 2019).
bacterial infection (1 paper, 2022). "In this study, KLF10 was identified as a major transcription factor downstream of AhR in response to a bacterial infection in mosquitoes." (PMID 35397616, 2022). "In this study, we demonstrate that mosquito AhR and KLF10 mediate a transcriptional axis that directs a transcriptional regulatory network in the immune context using a bacterial infection model." (PMID 35397616, 2022).
KLF10 also shares sentences with these, for which no sentence is quoted: Depression (2 papers); Glucose intolerance (2); immune disease (2); myopathies (2); Anxiety (1); cardiovascular disease (1); cataract (1); cognitive deficits (1); colitis (1); COVID-19 (1); glioblastoma (1); glycogenosis (1); hepatocellular carcinoma (1); hypertriglyceridemia (1); ischemic cardiomyopathy (1); leiomyoma (1); liver (1); lung squamous cell carcinoma (1); memory impairment (1); muscle atrophy (1); non-Hodgkin B-cell lymphoma (1); osteoarthritis (1); rectal cancer (1); renal carcinoma (1); sarcopenia (1); skin cancer (1); systemic sclerosis (1); triple-negative breast carcinoma (1).